STAT3 (signal transducer and activator of transcription 3)
Diseases named in the same sentence as STAT3 in open-access papers (continued):
Sharing a sentence is not in itself a finding about the gene and the disease.
breast cancer (continued). "Weak miR-124 expression might enhance Stat3 expression and radiotherapy resistance in HER2-positive breast cancer cells." (PMID 27815936, 2016). "Notably, we found that increased expression of phosphorylated STAT3, STAT3, and survivin correlated with a poor response to radiotherapy in HER2-positive breast cancer tissues." (PMID 26755645, 2016). "Mu and his team studied the underlying molecular mechanisms, and results showed that glabridin attenuated the angiogenic ability via inhibition of microRNA-520a (miR-520a)-mediated NF-κB/IL-6/STAT-3 signalling, the VEGF secretion, and the angiogenesis in MDA-MB-231 breast cancer cell line." (PMID 27999314, 2016). "Studies involving breast cancer stem cells revealed that STAT3 binds to and activates hTERT promoter in concert with Cluster of Differentiation 44 (CD44) and NF-κB, and that diminished levels of STAT3 resulted in the downregulation of hTERT expression." (PMID 27548225, 2016). "On the other hand, STAT3 in cooperation with NANOG maintains embryonic stem cell pluripotency and is essential for preservation of stemness characteristics, proliferation and tumorigenicity of CSCs in breast cancer and glioblastoma." (PMID 26862521, 2016). "While our previous work found that SH003 inhibits STAT3 in MDA-MB-231 breast cancer cells, this did not occur in DU145 prostate cancer cells." (PMID 27927199, 2016). "One interpretation of these results is that disruption of PDGFR-β/PDGF-B signaling may be important to block activation of STAT3 signaling, due to the effects of imatinib on inhibition of PDGFR phosphorylation in breast cancer." (PMID 27259262, 2016). "We have previously shown that blocking STAT3/5 using the small molecule inhibitor, SH-4-54, which targets the SH2 domains of both proteins, increases xCT expression, thereby increasing system xc- activity in human breast cancer cells." (PMID 27513743, 2016). "Moreover, STAT3 is a well-known key pathway downstreamer of EGFR and a promoter to the epithelial to mesenchymal transition (EMT) in breast cancer, through which Anxa 2 promotes EMT in dependence on STAT3 pathway." (PMID 27274723, 2016). "Therefore, given that clinical trials evaluating Il-6/JAK/ STAT inhibitors in breast cancer patients are under way, it would be important to determine the role of STAT1 and STAT3 in this disease." (PMID 27769057, 2016). "Indeed, miR-7 modulates the histone methyl transferase SETDB1, regulating a STAT3-dependent EMT, and acquisition of SC traits in CD44+ cells derived from MDA-MB-231 human breast cancer cells." (PMID 25774169, 2015). "Our study indicates that apigenin induces apoptosis through inhibition of STAT3 signalling and could serve as a useful compound to prevent or treat HER2-overexpressing breast cancer." (PMID 26500281, 2015). "Therefore, higher expression of miR-146b was positively correlated with patient survival in breast cancer subtypes with increased IL6 expression and STAT3 phosphorylation." (PMID 26697428, 2015). "Moreover, analysis of gene expression data in breast cancer patients revealed a significant correlation between GRN expression and STAT3 gene signatures, increased tumor grade, and reduced patient survival." (PMID 26000098, 2015). "Indeed, we detected the presence of GRN in both cytoplasmic and nuclear fractions of breast cancer cells, and silencing GRN reduced STAT3 DNA binding and target gene expression in SK-BR-3 cells." (PMID 26000098, 2015). "In breast cancer cells, increased promoter methylation of miR-146b results in inhibition of the negative feedback loop and increased expression of STAT3." (PMID 26097876, 2015). "Given that GRN is necessary for maximal STAT3dependent gene expression in breast cancer cells in vitro, we considered whether GRN expression is also correlated with STAT3-dependent gene expression in vivo." (PMID 26000098, 2015).
breast cancer (continued). "Together, EGFRvIII overexpression might decrease the sensitivity of breast cancer cells to trastuzumab via constitutively activating EGFR downstream signals including ERK, AKT, and Jak1/STAT3." (PMID 26474285, 2015). "We also verified whether apigenin inhibits signal transducer and activator of transcription 3 (STAT3) signalling pathway, leading to growth suppression of HER2-expressing breast cancer cells." (PMID 26500281, 2015). "Examples of such nodes in our present study are STAT3, STAT5A and myosin light chains, whose validity was supported by in silico survival curve analysis and immunohistochemical examinations of their usefulness as prognosis markers of breast cancer." (PMID 26479444, 2015). "Stat3 activity is significantly higher in MDA-MB-231BR and BT-474BR cells than in their wild-type counterparts, indicating that Stat3 was constitutively activated at higher levels in brain metastatic breast cancer cells." (PMID 25881542, 2015). "STAT3 is activated by JAK1–2, and the JAK1–2 inhibitor ruxolitinib has been approved by the FDA for the treatment of myelofibrosis and polycythemia vera, and is currently being tested in pancreatic and breast cancer clinical trials." (PMID 25762644, 2015). "Furthermore, inhibition of Stat3 by WP1066 decreased the incidence of brain metastases and increased survival in a preclinical model of breast cancer brain metastasis." (PMID 25881542, 2015). "Members of the interleukin-6 (IL-6) family, which are induced in a paracrine/autocrine fashion in breast cancer, mediate the activation of the Janus Kinase 2 (JAK2) and of the signal-transducer and transcription factor 3 (STAT3) promoting the expansion of mammary CSCs." (PMID 25774169, 2015). "Indeed, IL-6 has been demonstrated to activate STAT3/NF-κB signaling, which consequently sustains EMT in breast cancer, and to modulate the tumor microenvironment, linking inflammation to cancer progression and drug resistance." (PMID 26452030, 2015). "Our study indicated that EGFRvIII expression could decrease the sensitivity of breast cancer cells against trastuzumab via activating the ERK, AKT and Jak1/STAT3 pathways, which suggested that EGFRvIII inhibitor might reduce trastuzumab resistance." (PMID 26474285, 2015). "In addition, our in vitro assays demonstrated that the silencing of PTEN in HER2-amplified breast cancer cells was indeed able to activate the PI3K pathway and an inflammatory signaling cascade driven by the STAT3/NF-κB pathway." (PMID 26452030, 2015). "Chromatin immunoprecipitation analysis revealed that breast cancer cells treated with leptin and IL-6 (used as a positive control) showed increased recruitment of Stat3 at the miR-34a promoter while HNK treated cells showed decreased Stat3 recruitment." (PMID 26036628, 2015). "Moreover, we provided evidence that elevated STAT3 signaling mediates upregulation of MMP-2/9 and confers increased invasiveness in SK-BR-3/EPR breast cancer cells." (PMID 26501276, 2015). "In addition, EGF signaling can induce TWIST through a JAK/STAT3 pathway in epithelial cancer cell lines and the EGF–STAT3-positive correlation has been confirmed in primary breast carcinomas." (PMID 25763355, 2015). "Experiment was performed to examine the effects of EGCG on vascular endothelial growth factor (VEGF) production by YCU-H891 HNSCC and MDA-MB-231 breast carcinoma cell lines and found that treatment with EGCG inhibited the constitutive activation of the EGFR, Stat3, and Akt in both cell lines." (PMID 25977926, 2015). "STAT3 was activated by IL-6 in myeloma and prostate cancer cells, hepatocyte growth factor (HGF) and its receptor (c-MET) in leiomyosarcoma and breast cancer cells, and Src in breast cancer and melanoma cells." (PMID 24675568, 2014). "Breast cancer cell lines were genetically silenced or pharmacologically inhibited for CXCR7 and/or its downstream target signal transducer and activator of transcription 3 (STAT3)." (PMID 24886617, 2014).
breast cancer (continued). "If further studies can establish if RUNX1 overexpression and STAT3 activation are conserved in human breast cancer, and in TNBC in particular, this could pave the way for new treatment options based on the use of STAT3 inhibitors." (PMID 24967588, 2014). "Proteomic analysis of MDA231 CM identified IL-6 as a cytokine regulated by ezrin (data not shown) and the IL-6/Stat3 signaling loop has been reported to promote angiogenesis and metastasis in breast cancer." (PMID 25231728, 2014). "When lymph node expression was compared to its paired primary breast cancer expression, there was greater expression of cytoplasmic STAT1 (∼3.1 fold), phospho-STAT3(Ser727) (∼1.8 fold), and STAT5 (∼1.5 fold) and nuclear phospho-STAT3(Ser727) (∼1.5 fold) in the nodes." (PMID 24728078, 2014). "Expression levels of STAT1 and STAT3 transcript were then analyzed in 550 breast cancers from publicly available gene expression datasets (GSE2990, GSE12093, GSE6532), and protein expression was measured in an independent cohort of 546 primary breast cancers." (PMID 24728078, 2014). "In primary breast cancer, interleukin-6 (IL-6) induced activation of its downstream effectors, JAK2 and STAT3, and this signaling played a critical and pharmacologically targetable role in orchestrating the composition of the tumor microenvironment that promotes growth, invasion, and metastasis." (PMID 25405202, 2014). "STAT3 was constitutively phosphorylated in both, SKOV-3 and NCI-H596 cells, but also in IDO-negative cancer cell lines such as HepG2 hepatocellular carcinoma and MCF7 breast carcinoma cell lines." (PMID 24657910, 2014). "We demonstrate that the ALDH+ and ALDH+/CD44+/CD24− subpopulations of breast cancer cells expresses higher levels of phosphorylated STAT3 (Tyrosine 705) (P-STAT3, Y705) than cell populations that do not express these stem cell markers." (PMID 24376586, 2013). "This study reveals that two sorafenib analogues, SC-1 and SC-43, that do not inhibit raf-1 kinase activity, show better anti-cancer effects in human breast cancer cells than sorafenib and that this improved efficacy is mediated by SHP-1-dependent p-STAT3 inhibition." (PMID 23938089, 2013). "To further characterize the function of CRIP1 in breast cancer, particularly its role in cell signaling and proliferation processes, we investigated the phosphorylation status of several signaling molecules (MAPK, STAT3, PTEN and Akt)." (PMID 23570421, 2013). "Notably, the two highest expressed reporters were STAT3 and NF-κB, both well-known drivers of the EMT in breast cancer, as well as other cancers." (PMID 23776679, 2013). "Furthermore, a novel STAT3 inhibitor, LLL12, suppresses ALDH+ and ALDH+/CD44+/CD24− subpopulations of breast cancer cells in vitro and inhibits tumor growth in mouse xenograft and mammary fat pad models in vivo." (PMID 24376586, 2013). "In addition, we defined the molecular cross-talk between STAT3, hTERT and CD44 signaling pathways in aggressive breast cancer cells." (PMID 24386318, 2013). "The constitutive activation of STAT3 is frequently detected in primary mammary cancer specimens as well as in established breast cancer cell lines, but not in normal mammary epithelial cells." (PMID 24376586, 2013). "In mouse mammary tumor cells, knockdown of STAT3 strongly inhibits tumor invasion without affecting cell proliferation, supporting the notion of a specific role of CD44-STAT3 signaling in cancer cell invasion." (PMID 23326564, 2013). "In addition, LLL12 inhibited STAT3 downstream target gene expression and induced apoptosis in ALDH+ subpopulations of breast cancer cells." (PMID 24376586, 2013). "Furthermore, medroxyprogesterone acetate (MPA) can phosphorylate Stat3 at Tyr 705 and induce Stat3 nuclear localization in C4HD epithelial cells and T47D cell line of breast cancer, which can be reversed by RU486." (PMID 22511936, 2012).
breast cancer (continued). "Two breast cancer cell lines MCF7 (PTPMeg2 was depleted as it was endogenously high) and MDA-MB-231 (PTPMeg2 was overexpressed as it was endogenously low) were used to compare the level of phosphorylated STAT3 and the tumor growth ability in vitro and in vivo." (PMID 22394684, 2012). "Recent whole-genome expression profiling of breast cancers has revealed that the hypoxic response (predominantly through HIF-1α), the EGFR and signal transducer and activator of transcription 3 (STAT3) pathways are positively correlated together in TNBCs as compared to luminal cancers." (PMID 22225988, 2012). "Furthermore, inhibition of STAT3 expression and phosphorylation by PEITC treatment in our model indicated the inhibition of survival pathways in breast cancer cells." (PMID 22824293, 2012). "Also, it has been demonstrated that, by influencing specific second intracellular messengers, such as signal transducers and activators of transcription 3 (STAT3), AP-1, ERK2, and MAPK, leptin is involved in breast cancer cell proliferation and survival." (PMID 22701472, 2012). "SCC4 (head and neck squamous cell carcinoma), DU145 (prostate cancer), and MDA-MB-231 (breast cancer) cells expressing constitutive STAT3 were treated with or without EP." (PMID 22260501, 2012). "We hypothesized that HSE could suppress phosphorylation of STAT5 and STAT3, and the expression or release of IGF-1R, VEGF, VEGF-R2 and HIF-1α proteins in human breast cancer xenografts in vivo." (PMID 22792362, 2012). "We also observed inhibition of mitochondrial STAT3 by PEITC treatment in breast cancer cells (data not shown)." (PMID 22824293, 2012). "Interestingly, several of the elements identified in our computational analysis are bound by transcription factors such as STAT1, STAT3, STAT5, ETS1, PAX and E2F, which play important roles in mammary function and in breast cancer." (PMID 21655091, 2011). "Evidence reveals STAT3 is expressed in a variety of human malignancies, including leukemia, multiple myeloma, multiple melanoma, squamous cell carcinoma of the head and neck (SCCHN), breast cancer, prostate cancer, ovarian cancer and lung cancer." (PMID 22933956, 2011). "Although it has been reported that IL-6 and its downstream signal mediator, STAT3, can increase Twist expression through transcription in breast cancer cell lines, this does not exclude the mechanism of post-translational modification of Twist expression." (PMID 21559372, 2011). "Activated Stat3 mediated ATX up-regulation and enhanced migration of breast cancer cell lines." (PMID 22140473, 2011). "Activated Stat3 mediates signals downstream of the HGF/c-met pathway, and Stat3 has been shown to be essential for HGF-induced morphogenesis and for invasive behavior driven by c-met in both fibroblasts and breast carcinoma cells." (PMID 21595927, 2011). "FLLL32 also could inhibit STAT3 phosphorylation and induce apoptosis in MDA-MB-231 breast cancer cells." (PMID 20712901, 2010). "In addition, in our previous study, we demonstrated that STAT3 and AP-1 participated in regulating Her2 signaling-mediated MMP-7 expression in breast cancer cells." (PMID 20939893, 2010). "In addition, FLLL32 also potent to inhibit STAT3 phosphorylation and induce apoptosis in MDA-MB-231 breast cancer cells." (PMID 20712901, 2010). "We found that pretreatment with FLLL32 but not curcumin (20 μM) was able to inhibit the induction of STAT3 phosphorylation by IL-6 in MDA-MB-453 breast cancer cells, and the effect of FLLL32 was more potent than curcumin." (PMID 20712901, 2010). "Of note, STAT3 transcriptionally upregulates TWIST1 expression and promotes breast carcinoma cell migration prompting speculation that STAT3-TWIST1 interactions in GBM may also contribute to invasion and mesenchymal change." (PMID 20646316, 2010). "It is conceivable that BST2 may be an important regulator in the STAT3/BST2/IL6 pathway leading to increased cell migration and proliferation in the bone metastatic breast cancer." (PMID 19338666, 2009).
breast cancer (continued). "Inhibition of EGFR and Src kinases did not have an effect on pStat3, suggesting that these kinases are not direct mediators of Stat3 phosphorylation in these breast cancer-derived cell lines." (PMID 17531096, 2007). "Similarly, an inhibitor of EGFR was shown to inhibit Stat3 activation and it was shown that high EGFR was positively correlated with Stat3 in breast cancer." (PMID 17531096, 2007). "We found a single mouse mammary tumor cell line, LM3, that showed low levels of activated Stat3." (PMID 17925034, 2007). "Our studies have revealed a prominent and non-redundant role for IL-6 in driving Stat3 activation in breast cancer." (PMID 17531096, 2007). "The mechanisms of Stat3 activation have been presumed to involve multiple, redundantly acting growth factors and activated tyrosine kinases, making inhibition of one of these unlikely to lead to effective inhibition of Stat3 in breast cancer." (PMID 17531096, 2007). "Furthermore, Faecalibacterium prausnitzii is less abundant in breast cancer patients, which could suppress the growth of breast cancer cells through inhibition the JAK2/STAT3 signaling pathway." (PMID 40463381, 2025). "Since tumors containing both constitutively active STAT3 and STAT5 have distinct molecular and phenotypic profiles compared to tumors with constitutively active STAT3 alone, it is possible that the group of overlapping target genes play a considerable role in driving breast cancer severity." (PMID 40507264, 2025). "The STAT3 pathway is essential for tumor progression and aggressiveness, as it interacts with other pathways like Wnt and Notch in particular, triple-negative breast cancer (TNBC) which is the most aggressive form of breast cancer, with a poor prognosis and rapid metastasis." (PMID 40952540, 2025). "Furthermore, we identified cells within STAT3-positive (STAT3+) and STAT3-negative (STAT3-) breast cancer subtypes, as well as across various sectors of normal breast tissue." (PMID 40636126, 2025). "This could suggest a potential role for STAT3 in the Hippo signaling pathway in breast cancer, specifically modulation of STAT3 activity in response to mechanical stimuli rather than chemical stimuli." (PMID 40507264, 2025). "Notably, sEV TGF‐β+ did not significantly affect the closely related bone morphogenetic protein (BMP)‐SMAD1/5 signalling in breast cancer cells, nor did it impact the interleukin 6 (IL‐6)/signal transducer and activator of transcription 3 (STAT3) signalling." (PMID 40091448, 2025). "In breast cancer cells, HMGB1 translocation from the nucleus to the cytoplasm increased the JAK2-STAT3 interaction and induced STAT3 phosphorylation, leading to increased STAT3 target signaling, including the epithelial-mesenchymal transition (EMT) phenotype and PD-L1 expression." (PMID 40389855, 2025). "Preliminary research shows that the PDP1 gene is overexpressed in breast cancer tissues and correlates with poor prognosis, Validation through in vivo and in vitro experiments further confirmed that PDP1 contributes to cancer progression by regulating STAT3 phosphorylation levels." (PMID 40746885, 2025). "Thus, consistent with the findings of previous studies, the STAT3 pathway inhibition and DOXO treatment may enhance the antitumor effects of these agents in breast cancer cells." (PMID 40952540, 2025). "However, STAT3 and STAT5 can bind to a subset of overlapping genes, where in some cases, it has been demonstrated that STAT3 and STAT5 can compete for DNA-binding and transcriptional control of certain target genes in breast cancer." (PMID 40507264, 2025). "Additionally, in triple‐negative primary breast cancer, TC‐PTP deficiency enhances cell proliferation by strengthening Src family kinase (SFK) and STAT3 signaling pathways." (PMID 40166646, 2025).